STAT3 (signal transducer and activator of transcription 3)
Diseases named in the same sentence as STAT3 in open-access papers (continued):
Sharing a sentence is not in itself a finding about the gene and the disease.
prostate tumor (49 papers, 2006 to 2025). "We show that loss of Stat3 accelerates malignant progression of prostate tumours through abrogation of p19ARF expression, which we identified as a novel direct Stat3 target gene." (PMID 26198641, 2015). "Previous studies reported that IL6/Jak/Stat3 pathways is operating at multiple levels during prostate tumor progression." (PMID 39865080, 2025). "Previous studies have shown that STAT3 is also an oncogenic protein that promotes primary prostate tumors and metastatic lesions in PCa." (PMID 40374533, 2025). "Jun depletion in a Pten-deficient background prevented immune cell attraction which was accompanied by significant reduction of active STAT3 and IL-1β and accelerated prostate tumor growth." (PMID 38811984, 2024). "Another study suggests that EGF receptor‐mediated prostate tumour progression is dependent on STAT3, which regulates the expression of VASP (motility‐limiting vasodilator‐stimulated phosphoprotein), and the apoptosis nexus CASP3." (PMID 39641316, 2024). "TAM-released IL-8 was demonstrated to sufficiently drive prostate tumor formation by modulating the STAT3/MALAT1 axis." (PMID 36117852, 2022). "STAT3 positively affects the phenotypic transition from M1 into M2 mediated by prostate tumor cell-culture supernatant." (PMID 36117852, 2022). "In turn, SEPT2 induces JAK/STAT3 signaling to dually increase growth and viability of prostate tumor." (PMID 35773731, 2022). "Intriguingly, prostate-specific IL-6 transgenic mice exhibit, in addition to autonomously induced IL-6/STAT3/IGF signaling axis-mediated prostate neoplasms, an amplification of PPAT inflammation." (PMID 35406450, 2022). "Immunohistochemical staining revealed that Capz decreased constitutive p-STAT3 expression in prostate tumor tissues compared to the control group." (PMID 27458171, 2017). "Human prostate tumors with IL-6 elevation and loss of ESE3/EHF were associated with STAT3 activation and displayed upregulation of genes related to cell adhesion, cancer stem-like and metastatic spread." (PMID 27732936, 2016). "These therapeutic effects are due, at least in part, to functional depletion of STAT3 in prostate tumor tissue as well as in the surrounding areas of tumor cell invasion." (PMID 27435207, 2016). "The proof-of-principle experiments using CpG-siRNAs to target tumorigenic NF-κB/RELA and STAT3 signaling in xenotransplanted TLR9+ prostate tumors confirmed therapeutic efficacy of such strategy." (PMID 26046794, 2015). "To investigate the effect of STAT3 knockdown on prostate tumor cell tumorigenicity, we injected either STAT3 knock-down or control PC3M-1E8 cells subcutaneously into athymic nude mice and monitored tumor growth over 4 weeks." (PMID 25261365, 2014). "After androgen ablation, B cell infiltration into prostate tumor results in increased production of LT and activation of IKKα and STAT3 to promote the emergence of CRPC." (PMID 24475900, 2014). "Indirubin inhibited prostate tumor growth mainly through antitumor angiogenesis via blocking VEGFR-2 mediated STAT-3 signaling pathway in endothelial cell." (PMID 22554053, 2012). "It is quite reasonable that the high expressed pSTAT3 in prostate tumour tissues is from the increased expression of STAT3 as well as activation by autocrine growth factor signalling." (PMID 16804520, 2006). "We also found increased expression of STAT3 protein in prostate tumour tissues compared to normal tissue from the same patient (data not shown, as similar data have been previously published)." (PMID 16804520, 2006). "Previous data from other groups shows higher phospho-STAT3 expression in prostate tumour tissues than in adjacent normal tissues, and that this correlates with invasiveness." (PMID 16804520, 2006).
prostate tumor (continued). "Several studies have shown that IL-6 and its downstream transcription factor STAT3 have been identified as core mediators involved in several steps of prostate tumor progression, including tumor initiation, tumor growth regulation and promotion of tumor metastasis." (PMID 36733309, 2023). "Indeed, it was demonstrated in a prostate-specific IL-6 transgenic mice that IL-6 autonomously induces prostate neoplasm secondary to the activation of STAT3/IGF signaling." (PMID 35406450, 2022). "Upregulation of STAT3 promotes metastasis of prostate tumor to bone." (PMID 35773731, 2022). "And studies have found that in mice bearing TC1 murine prostate tumors, whether they were treated with antiandrogen therapy or silencing of AR, the expression of IL-6 and STAT3 in mouse tumors would increase." (PMID 33995485, 2021). "Antisense oligonucleotides provide another distinctly different approach to inhibit cellular STAT3, inhibiting immunosuppressive MDSCs and enhancing anti-tumor immunity, which could effectively eradicate prostate tumors in a mouse model." (PMID 32824865, 2020). "However, how STAT3 activation is regulated to promote progression of prostate tumors is still unclear." (PMID 31530281, 2019). "Analysis of RNAseq data for 52 normal prostate (control) and 498 prostate adenocarcinoma obtained from TCGA database, revealed that LEP, LEPR, JAK2 and STAT3 are statistically significant downregulated in prostate tumors in relation to normal (control) prostate." (PMID 31671654, 2019). "Subsequent work reported that activation of Janus kinase-2/signal transducer and activator of transcription-3 (Jak2/Stat3) pathway in PTEN-null senescent prostate tumors established an immunosuppressive tumor microenvironment thereby leading to its growth and chemoresistance." (PMID 31137607, 2019). "Furthermore, it has been shown that the combination of other pharmacological inhibitors of HIF-1α and STAT3 enhanced prostate tumor growth suppression." (PMID 30347860, 2018). "In addition, it was reported that elevated ROS produced by prostate tumor initiating cells was required for the activation of IL-6/STAT3, which was related with carcinogenesis of human prostate cells." (PMID 28947972, 2017). "IL-6/STAT3 is involved in the communications between prostate tumor cells and the microenvironment." (PMID 27611945, 2016). "Use of STAT3 dominant-negative (DN) and constitutive active mutants in fibroblast and human prostate tumour cells provided results consistent with the antisense approach and demonstrated that while STAT3 signalling is required it is not sufficient for the migratory and invasiveness phenotype." (PMID 16804520, 2006). "Interestingly, prostate tumour cells have been found to contain constitutively activated STAT3, and blockade of this activated STAT3 significantly suppressing the tumour cell growth." (PMID 16804520, 2006). "Our control study and the published results in prostate tumor models confirmed that concomitant TLR9 activation and STAT3 inhibition are necessary for the generation of effective antitumor effects." (PMID 38259453, 2023). "Inhibition of STAT3 activation reprograms the SASP and improves the efficacy of docetaxel-induced senescence by activating immunosurveillance in PTEN−/− prostate tumors." (PMID 35614034, 2022). "It should be noted that IL-6 induced expression of COX2, which is important for CD16 induction on monocytes by activated platelets, is mediated by STAT3 in monocytic THP1 cells and prostatic tumor cells." (PMID 33488616, 2020). "Immunohistochemistry studies showed increased levels of STAT3 and IL-6, but low levels of programmed cell death protein 4 (PDCD4), in prostate tumor epithelial cells compared to adjacent perinormal prostate epithelial cells." (PMID 28467474, 2017). "IL-6, a cytokine which is elevated in prostate tumors, reduced the expression of PCAT29 in both DU145 and LNCaP cells by activating signal transducer and activator of transcription 3 (STAT3)." (PMID 28467474, 2017).
prostate tumor (continued). "In summary, we propose that levels of JUN and STAT3 potentially orchestrated via PTEN, determine progression stages of human prostate tumors by modulating the immune response through regulation of cytokines and interleukins as identified in the Jun-deficient murine PCa model." (PMID 38811984, 2024). "We speculate that during the treatment of ADT, the function of AR was inhibited, IL-6 and STAT3 were activated for compensation, and the expression of IL-6 and STAT3 promoted the increased synthesis of FGG, thereby promoting the growth of the prostate tumor." (PMID 33995485, 2021). "Plasmid-based Stat3 siRNA introduced by CaCl2 modified Hydroxyapatite (HAP) nanoparticles was able to lower the protein expression of Stat3 and p-Stat3 in prostate tumor bearing mice at the same time downregulated the expression of Stat3-associated downstream genes." (PMID 30847297, 2019). "Our findings are consistent with the study showing significantly higher levels of constitutively active STAT3 in primary prostate tumor specimens compared to matched adjacent nontumor tissues." (PMID 25261365, 2014). "Another justification for potentially targeting STAT3 in nonmetastatic CRPC is the fact that inhibition of STAT3 might prevent treatment-induced neuroendocrine-like prostate tumor phenotype, also termed as t-NEPC." (PMID 34067832, 2021). "HGFL+/+ TRAMP+ prostate tumors displayed prominent STAT3 phosphorylation, while prostate tumors from HGFL-/- TRAMP+ mice exhibited no detectable STAT3 activation." (PMID 24980820, 2014).
Crohn disease (47 papers, 2009 to 2025). A gastrointestinal disorder characterized by chronic inflammation involving all layers of the intestinal wall, noncaseating granulomas affecting the intestinal wall and regional lymph nodes, and transmural fibrosis. "The gene-gene interaction network of the biomarker gene indicates the involvement of STAT3 and IL-5 genes linked to Crohn's disease's postoperative recurrence." (PMID 37994325, 2023). "It has been reported that STAT3 phosphorylation at the surgical ileal margin was associated with severe recurrence in Crohn’s disease patients." (PMID 37994325, 2023). "The connection of the genotype rs744166 in the 2 intron of the STAT3 gene is associated with a number of chronic inflammatory diseases, including Crohn’s disease, disseminated sclerosis, and cancer." (PMID 35327350, 2022). "Overall, this study illustrated that increased STAT3 activity was associated with the pathogenesis and progression of Crohn's disease." (PMID 31321245, 2019). "Amongst genes in SNP-associated bins, we found Crohn’s disease-associated genes STAT3, ATG16L1 and MHC genes HLA-DWB, HLA-DRA and HLA-DQA252." (PMID 29402885, 2018). "GWAS have identified STAT3 as a susceptibility gene in both Crohn’s disease and AS, the latter in both Europeans and Han Chinese." (PMID 28791018, 2017). "In a large German cohort study, a significant association was observed between the minor allele of STAT3 rs744166 and Crohn's disease (OR = 0.83, 95% CI = 0.688–0.998, and P = 0.04)." (PMID 24864251, 2014). "STAT3 has been reported in over 151 PubMed articles as being associated with Crohn’s disease." (PMID 40427743, 2025). "Similarly, for Crohn’s disease, STAT3 was identified as a significant associated gene using the protein-based approach (p = 9.1 × 10−5), whereas the RNA-based approach did not yield statistical significance (p = 0.012)." (PMID 40427743, 2025). "Additionally, the STAT3 rs744166 risk allele “A” has been associated with increased cellular STAT3 activation in leukocytes in pediatric Crohn's disease patients." (PMID 31321245, 2019). "Disruption of murine Stat3 in hematopoietic cells causes Crohn’s disease-like immunodeficiency." (PMID 28222105, 2017). "Even though the carriage of STAT3 rs744166 risk “A” allele is relatively high in healthy individuals, which is 56.4% compared to 63.6% carriage in CD patients, it has been indicated in several studies that STAT3 rs744166 is associated with Crohn's disease susceptibility." (PMID 31321245, 2019). "In intestinal smooth muscle cells isolated from patients with Crohn’s disease, STAT3 activation increases TGF-β, connective tissue growth factor, and collagen I gene expression." (PMID 34941574, 2022). "Genome-wide association studies have revealed that IL23R and five additional genes involved in Th17 differentiation (IL12B, JAK2, STAT3, CCR6 and TNFSF15) are associated with susceptibility to Crohn’s disease." (PMID 36498596, 2022). "In this study, we investigate the role of STAT3 in the pathogenesis and progression of Crohn's disease, and more specifically, we examine the STAT3 signaling involving in innate lymphoid cell plasticity." (PMID 31321245, 2019). "In this context, TGF-β-mediated phosphorylation of STAT3 at S727 is involved in the fibrotic element of fibrostenotic Crohn’s disease." (PMID 31557909, 2019). "This study was mainly focused on investigating the role of STAT3 in the pathogenesis and progression of Crohn's disease." (PMID 31321245, 2019). "Taken together, these results implied a potential involvement of dysfunctional STAT3 activity in the chronic relapse of Crohn's disease patients." (PMID 31321245, 2019). "Recent studies have implicated the role of Stat3 in inducing a subset of pro-inflammatory IL-17-producing helper T cells (THi) Constitutive activation of Stat3 has been found in intestinal T cells from Crohn's disease patients." (PMID 19440292, 2009).
Crohn disease (continued). "We tested whether genes associated with Crohn's disease are also associated with ankylosing spondylitis and confirmed that the two diseases share associations at chromosome 1q32 near KIF21B, STAT3, IL12B, CDKAL1, LRRK2/MUC19, and chromosome 13q14." (PMID 21152001, 2010). "Our results demonstrated that the sustained chronic inflammation could induce the intrinsic resistance presented as P-gp over-expression in PBMC in Crohn’s disease through STAT3/Nf-κb pathway and this resistance might be reversed by combinational usage of P-gp inhibitors." (PMID 26324318, 2015). "This study of genes associated with Crohn's disease has identified definite genome-wide significant association with AS of SNPs at chromosome 1q32 near KIF21B, and experiment-wise association at five other novel-AS loci including STAT3, IL12B, CDKAL1, LRRK2/MUC19, and at chr13q14." (PMID 21152001, 2010). "Notch/STAT-3-driven Blimp-1/c-Maf axis is a common anti-inflammatory pathway in human CD4+ T cells, which was defective in Crohn's disease patients." (PMID 37396905, 2023). "Additional evidence points to increased expression of IL-22 in patients with Crohn’s disease through a Th1- mediated STAT1 and STAT3 activation, further implicating its role in innate immune activation." (PMID 35628427, 2022).
liver diseases (47 papers, 2007 to 2026). "Evidence has shown that STAT3 signaling is indeed deficient in early alcohol associated liver disease." (PMID 38162671, 2023). "Further investigations are necessary to explore the underlying mechanism of STAT3-induced lncRNA-H19 expression and fully characterize the in vivo functions of lncRNA H19 during liver injury and other liver diseases." (PMID 32483425, 2020). "Both STAT1 and STAT3 proteins have been implicated as essential components linking cytokines signals to transcriptional events in pathogenesis of liver disease." (PMID 25908103, 2015). "Moreover, chronic inflammation and tissue injury, as observed in various gastrointestinal and hepatic disorders, maintain persistent IL-6/STAT3 activation that supports the proliferation of mutated epithelial cells and contributes to tumor initiation and progression." (PMID 41267807, 2025). "STAT3 is strongly linked to liver injury, playing a significant role in the genesis of liver diseases; a common activator of STAT3 is IL-6." (PMID 40265012, 2025). "Signal transducer and activator of transcription 3 (STAT3) is crucial in the pathogenesis of liver diseases." (PMID 41409896, 2025). "Among the top 10 interacting proteins in protein abundances, STAT3 plays a key role in the pathogenesis of liver diseases." (PMID 40066227, 2025). "In a previous study, some transcription factors including NF-κB and STAT3 were connected to liver diseases." (PMID 38543164, 2024). "It is known that STAT3 plays a pivotal role in the pathogenesis of liver diseases and contributes to the development and progression of fibrosis in the liver, a transcriptional factor involved in immune responses, inflammation, and tumorigenesis." (PMID 36834506, 2023). "Based on previous research, JAK1/STAT3 signaling inhibition can relieve the inflammation and ameliorate liver disease." (PMID 37630721, 2023). "Activation of STAT3 signaling was also shown to promote fibrosis in pulmonary, cardiac, and liver disease." (PMID 35663306, 2022). "The signal transducer and activator of transcription-3 (STAT3) perform a critical role in the pathophysiology of liver disorders." (PMID 36297027, 2022). "The E2 component of the mitochondrial pyruvate dehydrogenase complex (PDC) is the key autoantigen in primary biliary cholangitis (PBC) and STAT3 is an inflammatory modulator that participates in the pathogenesis of many liver diseases." (PMID 34737337, 2021). "Altogether, these findings suggest that TM4SF5-mediated STAT3 activity for extracellular matrix modulation is involved in the progression of liver disease to HCC and that TM4SF5 appears to suppress NK cells during liver carcinogenesis." (PMID 34921636, 2021). "The proinflammatory cytokines IL-6 and TNF-α activate the transcription factors STAT3 and NF-κB, which if persistently stimulated can aggravate liver disease progression and HCC development." (PMID 32357520, 2020). "As an emerging CD4+Th cytokine, IL-22 plays an overwhelming hepatoprotective and regenerative roles in various liver diseases with the activation of STAT3 pathway." (PMID 32760208, 2020). "Further studies in large patient and control populations with more polymorphisms genotyped are definitely needed to elucidate the possible role of STAT3 polymorphisms in chronic HBV infection and HBV-related liver diseases." (PMID 29609539, 2018). "Studies are also needed to elucidate the underlying mechanisms related to the potential association between STAT3 polymorphisms and chronic HBV infection and HBV-related liver diseases." (PMID 29609539, 2018). "The expression of IL-6, one of the major STAT3-activating cytokines, and is elevated in human liver diseases and HCC32." (PMID 30250040, 2018). "It is suggested that the associations of STAT3 polymorphisms with the susceptibility of chronic HBV infection and the development of liver disease including HCC are complicated." (PMID 29609539, 2018).